CDH1 (cadherin 1)
Diseases named in the same sentence as CDH1 in open-access papers (continued):
Sharing a sentence is not in itself a finding about the gene and the disease.
tumor (continued). "If CDC20 is involved in tumor formation, then we expected that the bulk of the tumor suppressors targeted by the APC would rely on CDC20 activity, whereas the tumor promoters should be specifically targeted by CDH1." (PMID 32805721, 2020). "This clinical finding has added a new dimension to our knowledge about Cdh1 in addition to its role as a tumor suppressor." (PMID 32015681, 2020). "Pertaining to metastasis, research shows that suppression of the tumor suppressor gene, epithelial cadherin (CDH1), is a key factor in EMT as it allows for the tumor cell to detach from its primary tumor site and metastasize in a secondary site." (PMID 32316322, 2020). "For the tumor cell lines, the methylation levels were generally low in CDH1 and CDKN2Ap16, where in the latter, H2347, Calu1, and H441 are contrasting with distinct high methylation levels." (PMID 32605217, 2020). "The methylation ranges observed in the tumor samples differed between genes, with low methylation ranges for CDH1, similar to the observed range in the NSCLC cell lines." (PMID 32605217, 2020). "The promoter region of some tumor-suppressor genes, including CDH1 and MGMT, has been shown to become hyper-methylated during EBV-induced primary B-cell transformation." (PMID 32483241, 2020). "Cdh1 is a haploinsufficient tumor suppressor in mice and cooperates with the retinoblastoma protein to restrain proliferation." (PMID 33306668, 2020). "Stable inhibition of Cdh1 expression in vivo resulted in lower tumor incidence and smaller tumor burden compared with the control group." (PMID 32015681, 2020). "CDH1 down-regulation is responsible for cell detachment from each other, while extracellular matrix remodeling is important to allow tumor cell dissemination." (PMID 33348918, 2020). "There is also data of its direct influence on protumourigenic processes as a transcriptional regulator, repressing the key tumour suppressor loci CDH1 (E‐Cadherin) and influencing epithelial to mesenchymal transition (EMT)." (PMID 32010971, 2020). "Further, both carcinogen-initiated and allografted tumor cells expressed reduced levels of Cdh1, indicative of an increased tendency for an EMT." (PMID 32580156, 2020). "Among the tumor specimens with IDH mutation, mRNA levels of SEMA3B, SEMA3C, SEMA3D, SEMA3G, NRP2, PLXNA2, and CDH1 were significantly higher (p < 0.05), while SEMA3F, NRP1, ITGB3, ITGA5, and VEGFA genes were under-expressed (p < 0.05)." (PMID 33036421, 2020). "DNMT3b is upregulated in esophageal squamous cell carcinoma, and associated with hypermethylation of multiple tumor-associated genes such as DAPK, p16, or CDH1." (PMID 31712935, 2020). "Five molecules (DAPK1, TIMP3, GRIN2B, SLC5A8, and CDH1) are tumor suppressor genes consistently downregulated and/or hypermethylated in GC and in H. pylori infected children." (PMID 32117120, 2020). "As a member of the cadherin superfamily, CDH1 (E‐cadherin) expression is decreased and behaves as a tumour suppressor to block the migration, invasion and metastasis of numerous human carcinomas." (PMID 32885590, 2020). "While bound to CDC20, it acts in an oncogenic fashion and promotes tumor development; however, when bound to CDH1, the APC displays many tumor suppressive effects." (PMID 32805721, 2020). "The main mechanism underlying the tumor suppression function of Cdh1 is the inhibition of epithelial-mesenchymal transition (EMT), a key process for tumor progression." (PMID 32015681, 2020). "The reduction of CDH1 expression is thought to promote metastasis and is an established indicator for a poor prognosis in a variety of tumor entities." (PMID 32605217, 2020). "Cadherin-3 (CDH3) regulates cell migration and tumor growth by interacting with cadherin-1 in PC and is upregulated during early-stage PC." (PMID 33173782, 2020). "In particular, the worst patient survival rate among all cases analysed was seen in patients with tumours carrying CDH1 structural alterations." (PMID 32301282, 2020).
tumor (continued). "The function of cadherin-1 was to promote adhesion between adjacent cells and played a key role in cell development, tissue maintenance, and tumor inhibition." (PMID 31998788, 2020). "The potential role that CDH1 plays in cell biology and tumor development is different from CDC20, as it appears to act as a tumor suppressor." (PMID 32805721, 2020). "Researchers found that higher methylation values of four genes (RASSF1A, CDH1, CDH13, and APC) were significantly associated with several traits of poorer outcome (tumor stage, growth pattern, muscle invasion, and tumor grade)." (PMID 33092083, 2020). "CDH1 is a tumor suppressor gene that contains 16 exons (100 kb), located in the chromosome 16q22.1, and encodes for E-cadherin, a transmembrane glycoprotein of 120 kDa." (PMID 32987716, 2020). "Enhanced expression of ITGA5 and vimentin (Vim) and reduced CDH1 (E-cadherin) expression were confirmed by immunoblotting in matched tumor epithelial cells." (PMID 30710055, 2019). "All tumors, irrespective of genotype, initially expressed high levels of CDH1, and only later, in the course of tumor development, did CDH1neg populations appear." (PMID 31189116, 2019). "Expression of S100A4, ACKR3, and CDH1 proteins in tumor samples from Doc-resistant and Doc-sensitive PCa patients was detected by western blotting and IHC." (PMID 31895690, 2019). "To directly assess the role of E-cadherin deletion in tumor progression, we generated Cdh1L/L:PtenL/L:PB-Cre4 compound mice, in which deletion of the tumor suppressor Pten and Cdh1 simultaneously occur in mouse prostatic epithelium." (PMID 31658259, 2019). "On the other hand, CDH1 was markedly downregulated in Doc-resistant tumor samples as compared to Doc-sensitive controls." (PMID 31895690, 2019). "The loss of E-cadherin (encoded by CDH1) is one of the most important hallmarks of EMT, and was demonstrated to be essential for tumor invasion." (PMID 31228948, 2019). "This characteristic is typical during the EMT process often occurring in tumor malignancy where, thanks to a switch between Cdh1 and Cdh2, tumor cells loosen cell-cell adhesivity." (PMID 31426573, 2019). "In a co-culture system, we observed that the effects of human bone marrow-derived MSCs (hBMSCs) on cancer cells were largely dependent on the expression of IL1β and CDH1 by tumor cells." (PMID 30993013, 2019). "Methylation analysis of the Cdh1, Cdh2, Mmp9, Mki67, Gfap, Gap43, Robo2, and Slit2 genes from tumor samples demonstrated that all of them were methylated in their promoter regions unlike those from normal tissues." (PMID 31921388, 2019). "GS tumours show RAS homologue gene family, member A (RHOA) and E-cadherin (CDH1) gene mutations and the Claudin-18 (CDLN18)-Rho GTPase activating protein 6/26 (ARHGAP6/26) translocation." (PMID 31235864, 2019). "Compared with the oe‐NC group, the volume and weight of tumour tissues in the oe‐CDH1 group decreased significantly (P < .05)." (PMID 31317666, 2019). "Compared with that in the para‐carcinoma tissues, the CDH1 level was decreased in the HCC tumour specimens." (PMID 31012192, 2019). "The regions with cisplatin responsive tumor cells are then replaced by CDH1-positive (Cis-RPF-Rep) tumors that are (or have become) refractory to cisplatin." (PMID 31189116, 2019). "High expression of Slug reduces the level of CDH1, promotes the transformation of epithelial cells into mesenchymal cells, and promotes the metastasis of tumor cells." (PMID 31466138, 2019).
tumor (continued). "Through the comparative analysis between tumor and matched adjacent normal tissue, we identified large-scale amplification of SOX2 (26/37) and TP63 (24/37) and deletion of CDH1 (25/37) in tumor tissues." (PMID 31695781, 2019). "We observed a statistically significant decrease in CDH1 mRNA in tumor samples with respect to normal adjacent tissues (log2 mean relative expression −4.76 ± 2.27 vs −3.77 ± 2.79; p-value = 0.025)." (PMID 31509966, 2019). "The expression changes were most pronounced in the 10% of tumours with the lowest CDH1 expression by rank." (PMID 30066183, 2019). "The cell-cell adhesion protein E-cadherin (CDH1) is a tumor suppressor that is required to maintain cell adhesion, cell polarity and cell survival signalling." (PMID 31467357, 2019). "CDH1 gene repression promoted by its promoter hypermethylation, plays a crucial role in tumor invasion and spread." (PMID 31850082, 2019). "In contrast, panobinostat-treated TU-BcX-2 K1 tumor explants increased CDH1 and suppressed VIM and CDH2 mRNA expression, potentially indicating trans-differentiation to a more luminal-like phenotype." (PMID 30845999, 2019). "miR-101 has been reported to act as a tumor suppressor by targeting CDH1 inhibitors, such as ZEB1/ZEB2 and EZH2 in different tumors, including GC." (PMID 31509966, 2019). "In vivo, A549 cells with silencing lncRNA H19, overexpression of CDH1 or reduced CDH1 methylation exhibited low tumorigenicity, reflected by the smaller tumour size and lighter tumour weight." (PMID 31317666, 2019). "Further analysis of the central compartment revealed frequent juxtaposition of what appeared to be two distinct tumor populations readily distinguishable by the expression of E-cadherin (CDH1)." (PMID 31189116, 2019). "We also observed that the CDH1 expression level was significantly reduced in metastatic tumour tissues compared with that in non‐metastatic tissues." (PMID 31012192, 2019). "The level of TRERNA1 was positively correlated with tumour metastasis and was negatively correlated with the expression of CDH1 in HCC tissues." (PMID 31012192, 2019). "Cdh1 is thought of as a tumor suppressor, perhaps due to its role in restraining the entry of cells into the cell cycle and maintaining genome stability." (PMID 31382469, 2019). "Although oncogenic RAS-expressing atg5−/- or atg7−/- cells display reduced tumor growth, we found that CDH1 expression was largely reduced in oncogenic RAS-expressing atg7−/- or atg5−/- tumors compared to oncogenic RAS-expressing Atg7+/+ or Atg5+/+ tumors." (PMID 30782064, 2019). "Increasing evidence shows that long non‐coding RNA H19 (lncRNA H19) and CDH1 methylation are involved in multiple tumours." (PMID 31317666, 2019). "For this purpose, four tumour-suppressor genes: Ras Association Domain Family Member 1 (RASSF1), Paired Box 1 (PAX1), Cadherin 1 (CDH1) and Phosphatase and Tensin Homolog (PTEN) were analysed." (PMID 31450846, 2019). "CDH1 is important for cell adhesion and when usually silenced by methylation can lead to metastasis and tumor progression." (PMID 31366565, 2019). "Among the miRs filtered by in silico analysis as direct/indirect regulators of CDH1 expression, miR-34c, miR-506, miR-217, miR-199a, miR-153, and miR-544 were undetectable in both normal and tumor samples from a cohort of 17 IGCs." (PMID 31509966, 2019). "In most cancers with epithelial origins, CDH1-mediated cell-cell adhesion is lost concomitantly with the acquisition of an invasive phenotype, high tumor grade, and low patient survival." (PMID 31208279, 2019).
tumor (continued). "The activation of these transcription factors drives tumor invasion and metastasis, inducing the transition to mesenchymal characteristics by repressing the transcription of CDH1 and activation of mesenchymal CDH2." (PMID 31275381, 2019). "MiR-9 was shown to be responsible for the negative regulation of the CDH1 gene, leading to tumor progression and invasiveness." (PMID 29879907, 2018). "This binding leads to the recruitment of CtBP corepressors ultimately resulting in repressed CDH1 transcription and leading to epithelial mesenchymal transition (EMT), a hallmark of tumor invasion and metastasis." (PMID 32309604, 2018). "Another biomarker of interest in carcinogenesis, E- cadherin (CDH1) a single pass transmembrane protein is involved in epithelial to mesenchymal transitions (EMT) resulting in tumor progression and transition to a more motile and invasive phenotype." (PMID 30383826, 2018). "Among these genes E-cadherin (CDH1) is a tumor suppressor involved in epithelial cell-cell interactions." (PMID 30143675, 2018). "Immediately after surgery, tumor samples were frozen in liquid nitrogen and stored in a biofreezer at –80°C for assessment of E-cadherin 1 (CDH1), SLUG (SNAI2), and NCAM (NCAM1) by real-time PCR." (PMID 29267504, 2017). "Reduced expression of epithelial markers, especially of the cell-cell adhesion molecule CDH1 (E-cadherin), contributes to cancer cell detachment from the primary tumor." (PMID 29156750, 2017). "Epigenetic silencing of tumour suppressor genes like CDH1 are key events in tumour development and progression." (PMID 28555645, 2017). "By multiplex dPCR, we compared the expression levels of CDH1 in tumor and corresponding normal tissue samples from 21 IGC patients." (PMID 27861150, 2017). "Two of the established tumour suppressors, CDH1 and MAP2K4, fall within known fragile sites FRA16B and FRA17A, respectively." (PMID 29089486, 2017). "In agreement with the transcriptional profile, immunostaining of patient tumor sections showed that CDH1 was only present in the choroidal tissue while CDH2 manifested an opposite pattern." (PMID 28246385, 2017). "For example, we identified a cluster of mutations that likely disrupt critical calcium-binding sites in CDH1, a tumor suppressor that mediates cell adhesion." (PMID 28115009, 2017). "CDH1 gene inactivation by promoter methylation in cancer contributes to the increase in the proliferation, invasion, and metastasis of tumor cells." (PMID 28926589, 2017). "Multivariate analysis showed an independent association between CDH1 expression and better RFS and OS (p< 0.05) beyond tumor size, nodal status, and grade." (PMID 29100362, 2017). "Among genetic lesions, CDH1 inactivating mutations are a typical feature of DGC, while promoter hypermethylation and LOH have been found in both tumor histotypes, albeit at different frequencies." (PMID 27861150, 2017). "Aberrant Cdh1 activity or ablation of Cdh1 deprives its role of tumor suppression, thus contributes to carcinogenesis and other diseases." (PMID 27902968, 2017). "Multiple tumor-related genes are found to be commonly methylated in tissue samples in GC, such as p16, CDH1, RUNX3, MLH1, RASSF1A, p15, APC, DAPK, GSTP1, Reprimo, and MGMT etc.." (PMID 29100425, 2017). "By using protein structures, we identified potentially inactivating mutational clusters in critical regions of several tumor suppressors including PTEN, CDH1, and KEAP1." (PMID 28115009, 2017).
tumor (continued). "Using RNA-Seq and real-time qPCR, CDH1 was shown to be up-regulated in recurrent muscle-invasive cisplatin-resistant UCB tissue compared with adjacent non-tumor tissue." (PMID 28915599, 2017). "Further analysis revealed that most of these tumor cells expressed significantly reduced levels of Cdh1 protein when compared with levels in luminal cells of the mammary glands." (PMID 27811360, 2016). "Here we report that in various tumor cells, Cdh1, conversely, suppresses the E3 ligase activity of WWP2, another NEDD4 family protein, in an anaphase-promoting complex/cyclosome-independent manner." (PMID 27462441, 2016). "Down-regulation or inactivation of CDH1 has been frequently observed during tumor cell progression, and several mechanisms have been proposed." (PMID 26905733, 2016). "Top enriched GO processes found in FLO-1LM (vs. FLO-1 parental) and CDH1 low tumors (vs. CDH1 high tumours) were subsequently compared." (PMID 27863424, 2016). "RT-qPCR was subsequently repeated for five promising targets, in addition to E-cadherin (CDH1) for all the 15 patient tumor samples and four dura controls, using three reference genes (GAPDH, ACTB (β-Actin) and HPRT)." (PMID 26950155, 2016). "More importantly, mice deficient in Cdh1 were embryonic lethal, while Cdh1 heterozygous mice displayed a decrease in survival and were more susceptible to developing epithelial tumors, suggesting a tumor suppressor role for Cdh1." (PMID 27462441, 2016). "We further evaluated the relationships of CDH1 promoter methylation with clinicopathological features, such as tumor histology and tumor stage." (PMID 27067410, 2016). "Further results based on mouse targeting deletion or xenograft studies demonstrated that APC/C coactivator Cdc20 or Cdh1 to be as oncoprotein or tumor suppressor in many types of cancer." (PMID 27418942, 2016). "Recent findings showed that PRC2 was an important driver of tumor development and progression by suppressing various key genes, such as CDH1, DKKI and INK/ARF45." (PMID 27326854, 2016). "Introduction of latent membrane protein 1 (LMP1), a viral oncoprotein from EBV, into a breast cancer cell line (MCF-7) activated DNMT1, DNMT3A, and DNMT3B, and induced methylation-silencing of tumor-suppressor gene CDH1." (PMID 26823082, 2016). "For CDH1, there was a large variation in methylation between the individual tumor-derived DNA samples, with levels ranging from 4.50% to 67.60% across three probes." (PMID 27902704, 2016). "One of the hallmarks of EMT is the functional loss of E-cadherin (encoded by CDH1), which is thought to be a metastasis suppressor during tumour progression." (PMID 27453691, 2016). "Multivariate analysis showed that nuclear HDAC3 and cytoplasmic CDH1 (P = 0.001 and P = 0.010, respectively), as well as tumor differentiation (P = 0.009) are independent prognostic factors." (PMID 26918727, 2016). "CDH1, a tumor suppressor in different kind of cancers, is a pivotal protein in maintaining cell to cell junctions to hold the epithelial cells tight, collectively, through anchoring β-catenin to the cell membrane." (PMID 27801803, 2016). "E-cadherin, encoded by CDH1, plays a pivotal role in the inhibition of tumor invasiveness and malignancy, as well as suppression of EMT." (PMID 27657126, 2016). "CDH1, MLLT4 and CTNNA1 were deleted in 29, 7 and 1 tumours, respectively, and harboured inactivating mutations in 169, 20 and 4 tumours, respectively." (PMID 27161491, 2016). "The Cdh1-positive cells in the regenerated tumors accounted for < 5% of total tumor cells, however, they aggregated together and formed a larger mass of epithelial-like tissue than in primary tumors." (PMID 27811360, 2016).